MC1R (melanocortin 1 receptor)
Diseases named in the same sentence as MC1R in open-access papers (continued):
Sharing a sentence is not in itself a finding about the gene and the disease.
skin cancer (68 papers, 2008 to 2025). "The MC1R variant related to an increased risk of skin cancer is mediated by decreased levels of cAMP." (PMID 41002740, 2025). "Participants receiving MC1R higher-risk feedback reported a durable increased skin cancer perceived risk, although decreases in sun exposure hours were not sustained over the study period." (PMID 39682213, 2024). "Conclusions.MC1R genetic testing resulted in durable elevated skin cancer risk perceptions and shorter-term behavior changes among higher-risk individuals." (PMID 39682213, 2024). "We examined changes in skin cancer-related behaviors, distress, and beliefs over time after MC1R genetic testing and receipt of average-risk or higher-risk personalized feedback in 568 non-Hispanic White and 463 Hispanic participants." (PMID 39682213, 2024). "At the second follow-up, intervention effects on skin cancer-related beliefs persisted among Hispanic participants at MC1R higher risk." (PMID 39682213, 2024). "Our most robust study findings related to the impact of MC1R testing on risk perceptions with participants at MC1R higher risk reporting higher absolute risk and greater comparative risk for developing skin cancer compared with those at average risk." (PMID 39682213, 2024). "Another study in young adults (n=92) explored the impacts of personalized ultraviolet (UV) radiation photographs, genetic testing(MC1R)for skin cancer risk, and general skin cancer prevention education on sun-related behaviours (protection, tanning, sunburn)." (PMID 40199300, 2024). "At the second follow-up survey, i.e., at 12 months, only intervention effects for skin cancer-related beliefs persisted among NHW participants at MC1R higher risk." (PMID 39682213, 2024). "There were few statistically significant baseline differences in demographics, skin cancer-related behaviors, skin cancer-related distress, or skin cancer-related beliefs across participants who received MC1R higher- versus average-risk feedback." (PMID 39682213, 2024). "Skin cancer distress was low, and participants at MC1R higher risk only reported slight heighted skin cancer worry that dissipated over the course of the study." (PMID 39682213, 2024). "In the secondary data analyses reported here, we compared the effects of the precision prevention on skin cancer-related behaviors, distress, and beliefs, among participants at MC1R higher risk and MC1R average risk at the first of two follow-up surveys." (PMID 39682213, 2024). "Mutations in the MC1R gene are known to lead to decreased eumelanin production, which impairs UV protection and thus increases susceptibility to skin cancer." (PMID 37444464, 2023). "While FST appears to be the major factor predisposing to skin cancer in our collective, the MC1R genotype seems to predominate over FST: in a multivariate analysis, the MC1R genotype, but not the FST, remained significant." (PMID 36765822, 2023). "Skin fairness, UV damage, and an increase in skin cancer cases are related to polymorphisms in the specific gene melanocortin 1 receptor gene (MC1R)." (PMID 36986867, 2023). "Polymorphisms associated with loss of function of MC1R are also correlated with an increased incidence of the three commonest forms of skin cancer." (PMID 37275429, 2023). "We found a correlation between MC1R risk types and the number of skin tumors in individuals with a history of more than 5 or 10 NMSCs." (PMID 36765822, 2023). "“Researchers have found the MC1R gene variant increases the number of mutations in skin cancer cells, multiplying the risk” (SU030)." (PMID 34279845, 2022). "These included the skin cancer-associated MC1R c.85dupA (p.Asn29Lysfs*14) variant in multiple subjects in branches 6, 8, 10, and 11 in which one carrier (subject III.26) had a history of skin basal cell carcinoma." (PMID 36612224, 2022).
skin cancer (continued). "Receipt of MC1R precision prevention materials improved some skin cancer prevention behaviors among higher-risk participants and their children and did not result in reduced prevention activities among average-risk participants." (PMID 35845857, 2022). "The substantial interest and promising outcomes associated with MC1R genetic testing in dermatology patients inform intervention strategies to enhance benefits and minimize risks of skin cancer genetic testing." (PMID 35959144, 2022). "Our pilot study showed that 56% of Hispanics in Puerto Rico and the Tampa Bay area—including individuals with diverse ancestry backgrounds—carry MC1R variants associated with elevated skin cancer risk, with MC1R minor allele frequencies ranging up to 10%." (PMID 35845857, 2022). "Others described alterations to their prior preconceptions about skin cancer risk and prevention, which they attributed to participation in the study, especially the MC1R test and the UV photographs." (PMID 36225123, 2022). "Associations between MC1R variants and skin cancer are stronger in individuals with “sun-resistant” phenotypic characteristics (e.g., darker hair, scant freckling) than in those with “sun-sensitive” characteristics (e.g., red hair, easy burning, freckling)." (PMID 34439206, 2021). "First, what are the 3 month outcomes (i.e., overall sun protection, skin cancer screening, cancer worry) associated with the receipt of higher (compared to average) risk MC1R feedback?" (PMID 34439206, 2021). "We examined 3 month sun protection, skin cancer screening, and skin cancer worry outcomes associated with MC1R test offer and completion." (PMID 34439206, 2021). "An increased risk in the development of skin cancers has been associated with the combination of several environmental factors (i.e., ultraviolet exposure) and genetic background, including melanocortin-1 receptor (MC1R) status." (PMID 34356109, 2021). "Even though there are missense and nonsense polymorphisms in pigmentation genes strongly associated with skin cancer, particularly in the gene MC1R, it is not fully understood how non‐coding variation in these genes relates to malignancy." (PMID 33248005, 2021). "MC1R variants are recognized genetic risk factors for many diseases, and some SNPs are closely related to human hair color, skin color, and skin cancer." (PMID 34698109, 2021). "The well-established role of MC1R in skin cancer risk, which has been proven to be independent from skin phototype, highlights the importance of this gene in genetic testing and skin cancers’ prediction." (PMID 34356109, 2021). "For example, MC1R variants have been found in most red-haired people in Europe, and studies show that these people are more likely to suffer from skin cancer." (PMID 34698109, 2021). "As such, the MC1R genotype conveys information about inherited skin cancer risk for a broad spectrum of individuals, including Hispanics." (PMID 34439206, 2021). "Different patterns of moderators were seen for the effect of MC1R risk feedback level on the skin cancer screening outcome." (PMID 34439206, 2021). "Polymorphisms in the melanocortin-1 receptor, for example, have been linked to a higher risk of skin cancer." (PMID 34943797, 2021). "These associations were initially related to the pigmentary functions of MC1R, although many studies confirmed that the increased skin cancer susceptibility in MC1R carriers is independent from pigmentary traits." (PMID 34356109, 2021). "We further assessed associations between MC1R variation and traditional skin cancer risk factors and genetic ancestry in this population." (PMID 32350296, 2020). "Over half of participants carried MC1R variants known to increase risk of skin cancer, and there was diversity in the observed variants across sample populations." (PMID 32350296, 2020).
skin cancer (continued). "Among Puerto Ricans, the proportion of participants carrying MC1R variants imparting elevated skin cancer risk was consistent across quartiles of European, African, and Native American genetic ancestry." (PMID 32350296, 2020). "In previous studies, it has been confirmed that mutations of the MC1R gene were associated with melanin trait variation or skin cancer and other diseases in a number of mammalian species, such as human, mouse, cattle, horse, fox, pig, sheep, and dog." (PMID 27957493, 2016). "To date, there is a lack of information about the mechanisms underlying the increased skin cancer risk in carriers of CDKN2A mutations in association with MC1R variants." (PMID 24742402, 2014). "The aim of the study was to determine the constitutional effect of germline CDKN2A mutations or MC1R variants in skin cancer, in order to identify early critical molecular targets implicated in the disease." (PMID 24742402, 2014). "We studied the impact of the CDKN2A germinal mutation p.G101W and MC1R variants on gene expression and transcription profiles associated with skin cancer." (PMID 24742402, 2014). "Loss-of-signaling MC1R polymorphisms are commonly found among fair-skinned, sun-sensitive and skin cancer-prone populations (e.g., Northern Europeans)." (PMID 23749111, 2013). "Overall, there is much evidence placing MC1R as a critical determinant of skin cancer risk, and regulation of eumelanin by POMC derived peptides depends on genetic context." (PMID 23749111, 2013). "One of the most important alleles that influences skin cancer risk is the melanocortin 1 receptor (MC1R), whose function is central to the adaptive pigmentation (tanning) response in the skin." (PMID 23749111, 2013). "The joint contribution of MC1R variants and phenotypic characteristics to skin cancer development will be studied via logic regression modeling." (PMID 22862891, 2012). "In human beings, the role of various Mc1r variants has similarly been previously explored, particularly those showing strong associations to skin cancer development." (PMID 19119422, 2009). "The effect of discovered MC1R variants on the individual's pigmentation characteristics, or risk of skin cancer, remains to be elucidated." (PMID 18803811, 2008). "However, certain MC1R polymorphisms reduce MC1R signaling, leading to decreased eumelanin production and increased susceptibility to sunburn and skin cancer." (PMID 41002740, 2025). "A systematic review of gene–sun exposure interactions in skin cancer identified variants of MC1R, CAT, and NOS1 that could help explain the mechanism by which sun exposure causes CM." (PMID 39281383, 2024). "We evaluated how skin cancer-related behaviors, skin cancer-related distress, and skin cancer-related beliefs were impacted by the knowledge of MC1R genetic risk status, which provides insight into the potential benefits and harms that can accompany low to moderate genetic testing." (PMID 39682213, 2024). "Individuals with actinic keratoses had a 7.5-fold risk for skin cancer development, and those with green or blue eyes a 4.1- or 3.6-fold risk, respectively; carriers of particular MC1R genotypes associated with a diminished function had a 1.9-fold increased risk." (PMID 36765822, 2023). "Therefore, an additional UV effect on the development of skin cancer in carriers of medium- and high-risk MC1R variants can be neglected." (PMID 36765822, 2023). "In conclusion, we conducted a qualitative study that examined undergraduate students' overall experience with participating in an intervention that provided skin cancer education as well as personalized skin cancer risk information in the form of a UV photograph and/or MC1R genetic testing." (PMID 36225123, 2022). "However, it was notable that for some, their interpretations of the MC1R genetic test results and the UV photographs led to the underestimation of their overall skin cancer risk." (PMID 36225123, 2022).
skin cancer (continued). "In conclusion, provision of skin cancer precision prevention materials based on MC1R risk group can improve sunscreen use and tendency to undergo a TBSE among MC1R higher-risk Hispanics and may improve some primary prevention activities among their children." (PMID 35845857, 2022). "MC1R has been relevant to an increased susceptibility to skin cancer." (PMID 35872794, 2022). "The opportunity to be ‘tested for a genetic marker for skin cancer’ (Group 4) was appealing to participants who received MC1R testing, as many participants were unaware that variants could indicate an increased risk for developing skin cancer." (PMID 36225123, 2022). "Interestingly, a different collagen morphology and increased vascularization have been observed in subjects with atrophic photoaging, who are more likely to have skin cancer and to carry melanocortin-1 receptor gene (MC1R) polymorphisms." (PMID 34123564, 2021). "For example, MC1R polymorphisms were shown to be linked with an increased threat to skin cancer." (PMID 34943797, 2021). "It is likely that individuals with sun resistant phenotypes who carry MC1R risk genotypes may be unaware of their elevated skin cancer risk." (PMID 32350296, 2020). "This pilot study demonstrated that risk information based on MC1R genetic variants may be relevant to a diverse, Hispanic population and could inform skin cancer risk assessment, prevention and early detection recommendations in this setting." (PMID 32350296, 2020). "The MC1R gene polymorphisms have impacts on the plumage colors and skin traits in domestic animals; different alleles of the MC1R gene were associated with red hair color, fair skin, and skin cancer risk in human." (PMID 27957493, 2016). "The aim of the present study was to investigate the global molecular effect of germinal CDKN2A mutations (p.G101W) and MC1R RHC variants in the transcriptome of primary skin cells from individuals belonging to skin cancer prone families (familial melanoma pedigrees)." (PMID 24742402, 2014). "Towards this end, the melanocortin 1 receptor (MC1R), a frequently studied pigmentation and skin cancer susceptibility locus, is the obvious candidate, as it is well established that a homozygous MC1R R306X mutation causes light versus dark coat color in STPOs and many other dog breeds." (PMID 23555311, 2013). "We selected papers according to the following inclusion criteria: 1) observational studies on single-primary sporadic skin cancer cases with information on any MC1R variant or 2) control series with information on any MC1R variant and at least one phenotypic characteristic under study." (PMID 22862891, 2012). "We had previously genotyped 7 common MC1R variants among the NHS skin cancer controls." (PMID 18483556, 2008). "Some MC1R variants have been associated with skin cancer risk." (PMID 18402696, 2008). "Therefore, higher levels of ASIP expression may increase the risk of skin cancer by reducing MC1R activity and melanin production." (PMID 39003418, 2024). "Genomic testing of MC1R for skin cancer risk may promote behavior change across ethnically and racially diverse populations, especially among Hispanics, who generally have low skin cancer risk awareness." (PMID 34439206, 2021). "Additionally, considering that impaired function of MC1R has been related to an increased susceptibility to skin cancers, MC1R agonists and antagonists might be employed as a potential therapeutic approach." (PMID 34356109, 2021). "Indeed, in our cohort, MC1R:p.V60L was the most frequent alteration and it has been shown elsewhere to be responsible for a low eumelanin/pheomelanin ratio that is a risk factor for skin cancer." (PMID 33748184, 2020). "Skin cancer risk information based on melanocortin-1 receptor (MC1R) variants could inform prevention and screening recommendations for Hispanics, but limited evidence exists on the impact of MC1R variants in Hispanic populations." (PMID 32350296, 2020).
skin cancer (continued). "Among those who reported moderate to strong tanning ability, 53% carried either medium or high MC1R risk variants, and this group particularly stands to benefit from receiving information on their MC1R genotype as it may change their perceived skin cancer risk (from lower to higher)." (PMID 32350296, 2020). "Prevention and screening advice that incorporates MC1R genotypes may improve skin cancer risk awareness and risk reduction among Hispanics18, but evidence on MC1R variants and their associations with pigmentation characteristics in Hispanic populations is limited." (PMID 32350296, 2020). "In summary, the genes identified may help to reveal underlying molecular mechanisms associated with red hair color phenotype and future studies of these genes may provide insight to better understand the increased skin cancer risk observed in individuals harbouring loss-of-function MC1R variants." (PMID 28030792, 2017). "In conclusion, the data collected within the M-SKIP project are a valuable resource for investigating associations between MC1R variants and skin cancer, particularly for population subgroups, and may be an appropriate setting to better investigate the genetics of sporadic skin cancer." (PMID 22862891, 2012). "Even when adjustments for skin phenotype are made, an influence of MC-1R on skin cancer development is still evident suggesting that the MC-1R signaling pathway might play a yet undescribed role in cutaneous biology accounting for the association of MC-1R and skin cancer." (PMID 20126537, 2010). "For example, ERCC2 gene mutations have been shown to indirectly increase the risk of SC, and the Melanocortin receptor 1 (MC1R), which encodes melanocyte-stimulating hormone (MSH) receptors, has also been shown to be a risk factor for skin cancer." (PMID 36874118, 2023). "Not that I was worried about it, but I have been keeping them kind of updated on the fact that I was in a research study about skin cancer and that I had that statistic [elevated above average MC1R result], and so I told my parents’ (Group 3)." (PMID 36225123, 2022). "In particular, genes involved in pigmentary regulation, such as melanocortin-1 receptor (MC1R), are implicated in skin cancers’ development." (PMID 34356109, 2021). "The potential ability to modulate MC1R function for clinical benefit, especially in redheads, has long been an ambition in skin cancer biology, though to date an effective strategy has been elusive." (PMID 30787281, 2019). "Loss-of-function MC1R variants, which impair protein function, are associated with red hair color (RHC) phenotype and increased skin cancer risk." (PMID 28030792, 2017). "Individuals with defective MC1R signaling are prone to UV induced skin cancer not only because they have decreased pigmentation but also because they have a blunted DNA repair response." (PMID 27303435, 2016). "The melanocortin 1 receptor (MC1R) is a critical genetic locus involved in pigmentation, the adaptive tanning response and skin cancer susceptibility." (PMID 23749111, 2013). "In human population, the MC1R gene (MIM155555) has many polymorphisms; some of them have been identified with association with red hair, fair skin, freckling, and increased skin cancer risk." (PMID 24000325, 2013). "Loss of signaling MC1R alleles such as the RHC variants are associated with up to a four-fold increased lifetime risk of melanoma and other skin cancers." (PMID 23749111, 2013). "Nonetheless, the modest impact of MC1R precision prevention on changes in skin cancer-related behavior in our analyses highlight the need for additional content, such as the development of an action plan, to aid the translation of heightened risk perception to actual behavior changes." (PMID 39682213, 2024). "Polymorphisms associated with loss of function of MC1R are associated with an increased risk of photoageing, freckles, red‐hair and all types of common skin cancers, independent of these behavioural variables." (PMID 37275429, 2023).